C6 (complement C6)
Diseases named in the same sentence as C6 in open-access papers (continued):
Sharing a sentence is not in itself a finding about the gene and the disease.
infection (continued). "C6 is highly conserved in orthopoxviruses, and C6 orthologs from VACV, RPXV, CPXV-BR, CMLV, MPXV, and VARV all degrade HDAC5 outwith infection." (PMID 38461415, 2024). "In the present study, we observed an increase in the gene expression for complement including C6, C4A, CR2, C3 at 8wks post infection." (PMID 27467147, 2016). "VH1 is expressed late in infection and packaged into the virion, whereas C6 is an early VACV protein, expressed from approximately 2 h post infection." (PMID 27907166, 2016). "Nonetheless analysis of ISRE-driven gene expression early after infection with either wild type virus or a mutant virus lacking C6 showed a functional role for the C6 protein in diminishing ISRE-dependent gene expression." (PMID 27907166, 2016). "The immunomodulatory function of C6 is likely to be important during infection, as a deletion virus lacking C6 is attenuated in mouse models in vivo." (PMID 21931555, 2011). "However C6 was found down regulated in AFL, which is surprising as it is directly involved in the pathogen membrane attack complex and several complement B genes were found increased and decreased following infection." (PMID 20602791, 2010). "In addition, the expression of c1r, c6, c1qbp and c1qtnf6 in MOS200 or MOS400 groups were higher than that of the control group before or post-infection, which revealed the activation of these genes by dietary MOS and might enhance the anti-infection immunity of M. amblycephala intestines." (PMID 36768530, 2023).
tumor (9 papers, 2009 to 2025). "Immune and stromal cell populations included 2 populations: Macrophages 1 (c1: C1qa, C1qb, C3aR1, Cd68, Csf1r, Tlr2, and Cd86) and 2 (c6 + c9: Ccr7, Csf2rb, Il1b, and Cd74) expanded in PNs as a percentage of total tumor cells." (PMID 36134665, 2022). "In addition, multiple components of the complement system, a central mediator of RT-induced tumor-specific immunity, were upregulated — specifically, C1qa, C1qb, C1ra, C1s1, C3, C3ar1, C4b, and C6." (PMID 37345658, 2023). "It was suggested that that these findings may better account for the increased cellular motility in visceral tumors while the up-regulation of C6 (complement component 6) may represent the interactions of the innate immune response to the tumor cells." (PMID 29056712, 2016). "Serum C1q and C6 control the expression of WOX2 and may play a role in determining tumor progression." (PMID 19484134, 2009).
cancer (7 papers, 2009 to 2023). A tumor composed of atypical neoplastic, often pleomorphic cells that invade other tissues. "Since all these features are associated with the anti-cancer Vδ1+ NKp30+ γδ T cells in the blood of adult subjects, we propose that c6 in the post-natal thymus can be the source of these cells in the adult circulation." (PMID 36195611, 2022).
bacterial infection (1 paper, 2024). "Among these genes, certain genes involved in the complement cascade were expressed at lower levels in the resistant family (c2, c6, cr1 or cd59), in contrast to what was found in head kidney samples after bacterial infection." (PMID 39712009, 2024).
immune disease (1 paper, 2020). "The data presented show that three of seven proteins (ceruloplasmin, Complement C3 and Complement C6) are functionally implicated in immune disease and inflammatory response, DNA replication and cellular assembly and organization." (PMID 32620920, 2020).
C6 also shares sentences with these, for which no sentence is quoted: atherosclerosis (3 papers); Sepsis (3); atypical hemolytic-uremic syndrome (1); autoimmune disease (1); butyrylcholinesterase deficiency (1); co-infection (1); colorectal cancer (1); Ehlers-Danlos syndrome (1); endometriosis (1); fibrosis (1); fungal infection (1); glomerulonephritis (1); Heat Stroke (1); Hepatic fibrosis (1); inflammation (1); liver disease (1); malaria (1); mastitis (1); meningococcal meningitis (1); Parkinson ́s disease (1); pontocerebellar hypoplasia (1); primary immunodeficiency (1); pulmonary fibrosis (1); Recurrent infections (1); salivary gland disease (1); spastic paraplegia type 7 (1); synovial sarcoma (1); systemic lupus erythematosus (1); tenosynovial giant cell tumor (1); variola (1).
A further 2 diseases each share a sentence with C6 in 1 paper.